INS (insulin)
Diseases named in the same sentence as INS in open-access papers (continued):
Sharing a sentence is not in itself a finding about the gene and the disease.
Insulin resistance (continued). "The index of homeostasis model assessment insulin resistance (HOMA-IR) was calculated from insulin and glucose." (PMID 32546151, 2020). "Metformin had beneficial effects on maternal serum IGFBP-1 concentrations compared to insulin, possibly due to its favorable effect on insulin resistance." (PMID 32652973, 2020). "Obesity-related immune cell infiltration, inflammation, and increased oxidative stress promote metabolic impairments in the insulin-sensitive tissues and finally, insulin resistance, organ failure, and premature aging occur." (PMID 32793223, 2020). "Various actions have been recommended to overcome this insulin resistance as a first-line intervention, such as physical exercise, dietary and lifestyle modification, and insulin sensitizers." (PMID 32542134, 2020). "In these conditions, cells are unable to uptake the circulatory glucose in response to insulin resulting in insulin resistance." (PMID 32215179, 2020). "The current study suggests that the serum glucose, serum insulin level and insulin resistance were enhanced, whereas the cholesterol, HDL-C and ET-1 levels were reduced 30 min after TCC practice." (PMID 32784834, 2020). "While insulin resistance superimposing on the defective insulin secretion has been described for T2DM in obese individuals, its pathophysiology in the non-obese has been a dilemma since most of the proposed models have been done in obese subjects." (PMID 32399348, 2020). "In obesity, hyperinsulinemia occurs due to the hypersecretion of insulin and compensatory response to insulin resistance." (PMID 33158303, 2020). "Insulin resistance in adipose tissue is the inability of insulin to activate adipose glucose transport, promote lipid uptake, and suppress lipolysis." (PMID 32911464, 2020). "Surprisingly, RIDad mice had elevated levels of postprandial glucose and insulin and exhibited glucose intolerance and insulin resistance, even under chow-fed conditions." (PMID 32408016, 2020). "Due to its ubiquity in the insulin-targeted tissues and its role in insulin resistance development, inhibition of PTP1B activity would be a target for the treatment of T2DM and obesity." (PMID 33007997, 2020). "Type 2 diabetes (T2DM) is characterized by insulin resistance, wherein there is an overproduction and secretion of insulin in the early stage which lead to reduced insulin secretion and pancreatic beta cell death at late states." (PMID 33019646, 2020). "In particular, IL-6 and TNFα seem to directly interfere with the normal transmission of insulin signals, promoting the onset of insulin resistance and later the onset of type 2 diabetes." (PMID 33330284, 2020). "In conclusion, we report the effects of prolonged hyperinsulinemia in 3T3-L1 and SGBS, highlighting similarities and discrepancies between the cell types, to be considered when using these cells to model insulin-induced insulin resistance." (PMID 32718202, 2020). "Examining the gut microbiome composition in TLR5-deficient mice reveals that it was altered in such a way that it induced low-level inflammatory signaling, this in turn, attenuated insulin signaling to promote insulin resistance and hyperphagia." (PMID 31952471, 2020). "In the setting of insulin resistance, β-cells increase their insulin secretion (i.e., hyperinsulinemia) to maintain normal glucose levels (Johnson and Alejandro, 2008)." (PMID 33193730, 2020). "Here, we used congenic strains possessing different segments of Chr 11 from NSY mice in the control C3H genetic background to dissect the region of Chr 11 affecting hyperglycemia, impaired insulin secretion, and insulin resistance." (PMID 32703163, 2020). "In the liver, insulin resistance selectively impairs insulin-induced suppression of hepatic glucose production while insulin’s ability to suppress β-oxidation and promote lipogenesis remains intact." (PMID 32350271, 2020).
Insulin resistance (continued). "Insulin resistance is a hallmark of NASH, hence insulin sensitizers, such as PPARγ agonist thiazolidinediones (TZDs) and metformin, have shown efficacy in rodent models of NASH-HCC." (PMID 32443737, 2020). "Peripheral insulin resistance is a central feature of diabetes, but increasing evidence suggests that neuronal insulin signalling also regulates cognitive function." (PMID 31396860, 2020). "Prior studies reported on the relationship between insulin resistance that used fasting insulin and heart rate variability." (PMID 32393179, 2020). "The most vital physiological feature of T2D is insulin resistance, which is characterized by the impaired response to insulin in insulin‐sensitive tissues, and β‐cell failure resulting in β‐cell dysfunction and reduced β‐cell mass." (PMID 31793694, 2020). "Insulinemic status as per plasma insulin levels and homeostasis model assessment index of insulin resistance (HOMA-IR) scores were both significantly lower (p < 0.001) for the PEW compared to the NPEW group." (PMID 32708829, 2020). "The significant reduction in HOMA-IR and serum levels of insulin indicates that A. graveolens has a role to play in reducing insulin resistance." (PMID 32503652, 2020). "As a result, glucose uptake stimulated by insulin was decreased, ultimately leading to insulin resistance." (PMID 32332780, 2020). "Homeostasis model assessment of insulin resistance (HOMA-IR) scores were calculated using fasting insulin and glucose levels." (PMID 32493369, 2020). "In our systematic review, QPAD can not only increase ISI and decrease insulin resistance but also significantly reduce the INS, which provides a reliable evidence for the prevention of hypertension complications." (PMID 32802140, 2020). "High insulin levels in a context of insulin resistance are thought to modulate circulating microRNA expression." (PMID 32512799, 2020). "As T2DM starts to develop, the body comes to be less sensitive to insulin thus resulting in insulin resistance, which contributes to inflammation." (PMID 32659891, 2020). "In a study carried out in USA, MBP has been associated with poor insulin secretion, and MEP and MMP to insulin resistance assessed by Homeostatic model assessment of insulin resistance (HOMA-IR) index." (PMID 32764471, 2020). "Endothelial insulin resistance is characterized by a selective impairment of insulin activation of the PI3K/NO pathway in endothelium." (PMID 32851077, 2020). "In early stages of insulin resistance, the pancreas can compensate for impaired peripheral insulin action by increasing insulin production." (PMID 33178196, 2020). "The oral hypoglycemic medicines currently used in clinical practice are designed to target insulin resistance and/or glucose-stimulated insulin secretion." (PMID 31991596, 2020). "It is currently believed that the onset of T2DM is mainly related to factors such as genetics, insulin resistance, impaired insulin cell function, and obesity." (PMID 33181668, 2020). "Several parameter values were affected by the INSR genotype, particularly W/H ratio, lipid, insulin and glucose levels and insulin resistance in PCOS patients." (PMID 33033446, 2020). "It was widely accepted that ectopic adipocytes in skeletal muscle impaired insulin signaling and interacted with iWAT to induces or aggravates insulin resistance through glucose, fat metabolites or immune factors." (PMID 33291665, 2020). "Insulin resistance is referred to as a state where a normal, physiological concentration of insulin results in a reduced biological response of insulin-sensitive tissues." (PMID 32823892, 2020). "Consistent with a reduction in insulin resistance, there were also significant improvements in fasting insulin and fasting C-peptide levels." (PMID 32067166, 2020).
Insulin resistance (continued). "In T2DM and GDM, this impairment occurs in the setting of systemic insulin resistance, leading initially to hypertrophy and proliferation of pancreatic β-cells in order to increase insulin secretion capacity." (PMID 32595604, 2020). "Deletion of JNK1 specifically in adipocytes improved adipose tissue insulin action and suppressed liver insulin resistance induced by high-fat diet feeding." (PMID 32872540, 2020). "Overall, there is support for a model in which impaired insulin clearance promotes transient hyperinsulinemia or prolonged periods of higher insulin load that can promote insulin resistance in a manner that is secondary to variability in body weight." (PMID 32860984, 2020). "This insulin resistance is compensated for by an increase in the maternal functional β-cell mass and enhanced insulin secretory responses." (PMID 32106091, 2020). "When insulin resistance is high, the body continues to produce insulin even though there is a sufficient level of glucose." (PMID 32397662, 2020). "In performing this SIIT, we can get information about the relief of insulin resistance and glucotoxicity from the profile of glucose levels and insulin shot, and after then we can replace SIIT to maintenance therapy in FRD." (PMID 32005949, 2020). "Elevated levels of alanine aminotransferase (ALT) were the lowest in the MD group (p = 0.011) along with resistance to insulin (homeostasis model assessment-insulin resistance (HOMA-IR)), which was highest in the ND group (p = 0.001)." (PMID 32283773, 2020). "In obesity, IP6K1/5-IP7 mediated peripheral insulin resistance causes hyperglycemia, which further stimulates IP6K1/5-IP7 induced insulin secretion from β cells, resulting in hyperinsulinemia induced lipogenesis." (PMID 32204420, 2020). "Compared to TMFlox mice fed with HFD, TMLKO mice fed with the same diet showed lower fasting blood glucose, insulin, and homeostasis model assessment of insulin resistance (HOMA‐IR) levels." (PMID 32440483, 2020). "As a result, this persistent inflammatory condition leads to an impairment of insulin signalling, as well as exacerbating beta (β)-cell dysfunction and obesity-triggered insulin resistance, along with abnormal tissue remodelling and fibrosis." (PMID 33322742, 2020). "Inhibitors of iNOS improve hepatic insulin resistance in genetically obese mice, demonstrating the detrimental role of iNOS on impairing insulin signaling." (PMID 32429195, 2020). "Homeostasis Model Assessment (HOMA) of Insulin Resistance, Quantitative Insulin Sensitivity Check Index, McAuley, Matsuda, and Belfiore indices were calculated to evaluate the degree of insulin resistance (IR)." (PMID 32849275, 2020). "As a potent antioxidant, ASX reportedly improved insulin resistance through the JNK-IRS-1-Akt axis by suppressing insulin-induced JNK phosphorylation and IRS-1 serine phosphorylation in the liver of HFD mouse." (PMID 32260306, 2020). "High levels of circulating FFA are known to induce not only insulin resistance, but also defects in the insulin secretory capacity of β cells, as well as in insulin gene expression." (PMID 32668665, 2020). "Consistent with this, Ad-Piezo1-KO mice that received HFD exhibited a significantly reduced glucose tolerance, a modest increase in insulin resistance and increased insulin plasma levels." (PMID 32385276, 2020). "Chronic inflammation can affect the insulin sensitivity of the body and even lead to the occurrence of insulin resistance." (PMID 32595730, 2020). "At that time rats fed a high-fat diet plus blueberries had better measures of fasting insulin levels, insulin resistance (HOMA-IR), and glucose AUC than high-fat–fed controls." (PMID 31329250, 2020). "Estrogen is able to regulate insulin action by regulating oxidative stress, which contributes to insulin resistance, or by acting directly on insulin-sensitive tissues." (PMID 33348926, 2020).
Insulin resistance (continued). "We have identified genetic signatures that link PD with its comorbid disorders, narcolepsy and insulin resistance, from the convergence and intersection of dopaminergic, insulin, and immune system related signaling pathways." (PMID 34745571, 2020). "Based on this effect, glucose homeostasis indices, including insulin resistance, reduced insulin sensitivity, and β-cell dysfunction, were assessed in test rats that were induced to be diabetic." (PMID 33036127, 2020). "The liver is a key target of insulin and plays an important role in the development of insulin-resistance and type-2 diabetes." (PMID 32153503, 2020). "Recently, a novel non-insulin mediated driver of insulin resistance was proposed using an in vitro model of excitotoxicity." (PMID 33100956, 2020). "T2DM is characterized by the inability of pancreatic β-cells to produce enough insulin resulting hyperglycemia and the inability of insulin to bind with its receptors restrict the absorption of glucose (insulin resistance) into the cells." (PMID 32703184, 2020). "The PI3K/mTOR pathway has an essential role in the regulation of autophagy, which is disrupted in conditions such as insulin resistance and/or impaired insulin signaling (Calvo‐Ochoa & Arias, 2015)." (PMID 32170854, 2020). "It was revealed that JPXK prescription was capable of facilitating insulin secretion, enhancing insulin resistance, and effectively lowering blood sugar levels." (PMID 33456489, 2020). "Nevertheless, WSP-bioactive ingredients reduce not only blood glucose and insulin levels but also insulin resistance by improving the HOMA-IR index." (PMID 32425738, 2020). "Insulin resistance (IR) refers to impaired normal physiological function of insulin, therefore the target organs have reduced sensitivity to insulin." (PMID 32272794, 2020). "After 21 days of metformin intervention, the serum sex hormones, fasting blood glucose, fasting insulin, and insulin resistance (IR) of rats in each group were measured." (PMID 32988397, 2020). "Xiao and colleagues demonstrated an interaction between SLC47A1 rs2289669 and SLC22A1 rs594709, which affects the blood glucose, insulin level, insulin resistance and blood lipid improvement after metformin treatment in Chinese patients." (PMID 32961860, 2020). "In fact, some studies have reported a failure to find insulin resistance in hearts of the same type 2 diabetic patients in which other insulin target tissues, such as skeletal muscle or adipose tissue, exhibit a clear resistance to the action of the hormone." (PMID 31212580, 2019). "Glycated albumin, insulin, C‐peptide, proinsulin and homeostatic model assessment of insulin resistance were significantly reduced." (PMID 31033218, 2019). "Several key pathological abnormalities, including hyperglycemia, hyperlipidemia, insulin resistance, and abnormal insulin secretion because of impaired β-cell function, have been demonstrated to be involved in T2DM patients." (PMID 31354905, 2019). "Our data shows a lack of corroboration of whole-body insulin sensitivity measures (clamp) and fasting-based measures of insulin resistance (HOMA-IR, fasting glucose and insulin measures) with regard to association with genotype or methylation." (PMID 30641161, 2019). "GLP-1 is an intestinal insulin-stimulating peptide with functions such as reducing blood sugar and improving insulin resistance." (PMID 31396081, 2019). "T2DM development is characterized by both insulin resistance and impaired insulin secretion, with insulin resistance the most important feature in pre-diabetic states." (PMID 30642871, 2019). "The Homeostasis Model Assessment-Insulin Resistance (HOMA-IR) index is widely used as an indicator of fasting IR while the insulin sensitivity index (ISI) is an indicator of insulin-sensitivity." (PMID 31156553, 2019).
Insulin resistance (continued). "there was a high detection rate of people at risk for type 2 diabetes (59%)and the high and very high risk score was associated with high levels ofglycosylated hemoglobin A1c, glucose, insulin and insulin resistance, butnot with lipids." (PMID 31340346, 2019). "The quantification of insulin resistance based on the homeostasis model assessment (HOMA: insulin [ng/ml] × glucose [mM]) showed that insulin resistance was increased by approximately twofold in Kir6.1-null mice compared to WT mice." (PMID 31387986, 2019). "Iranian propolis has beneficial effects on reducing post prandial blood glucose, serum insulin, insulin resistance, and inflammatory cytokines." (PMID 31086222, 2019). "In the present study, PCS extract significantly reduced MGO-induced insulin resistance, resulting in the recovery of glucose uptake in the insulin-stimulated HepG2 cells." (PMID 31976027, 2019). "Glucose tolerance and insulin resistance (fasting plasma insulin) were impaired in group 2 (p < 0.05)." (PMID 31620011, 2019). "Insulin-mediated activation (phosphorylation) of insulin receptor substrate (IRS) proteins has been recognized as the major basis for linking insulin resistance to NAFLD." (PMID 30642126, 2019). "Under conditions of hepatic insulin resistance, the de novo lipogenesis can be stimulated both by insulin, via sterol regulatory element-binding-protein 1c (SREBP-1c), and by glucose, via carbohydrate response element-binding protein (ChREBP)." (PMID 31447675, 2019). "A defining feature of the (type II) diabetic phenotype is the presence of peripheral insulin resistance (IR), whereby this action of insulin is impaired." (PMID 31344028, 2019). "HOMA-IR is a marker of insulin resistance and beta cell function that is a noninvasive method used to compare insulin secretion and insulin resistance." (PMID 30866603, 2019). "Insulin resistance is a pathological manifestation that target tissues including liver, muscle, and adipose tissues are less sensitive to the effect of insulin." (PMID 31649547, 2019). "Currently, impaired insulin secretion and insulin resistance are generally accepted as pathological changes that lead to the development of diabetes." (PMID 31545909, 2019). "Next, we set up a novel chronic high insulin-based cellular paradigm to specifically address insulin resistance in cholinergic neurons and found that the IR-IRS-AKT signaling pathway is significantly downregulated in cholinergic neurons." (PMID 29736736, 2019). "Endothelial dysfunction is associated with cardiovascular conditions, like atherosclerosis, hypertension, hyperlipidemia, and insulin resistance, which alters the insulin signaling pathway." (PMID 31467596, 2019). "Although the BMIs and glucose levels were different between the two groups after 12 weeks intervention, there were no group, time, or group × time interaction effects observed for BMI, insulin and insulin resistance index (HOMA-IR)." (PMID 30678193, 2019). "In insulin resistance, the cells are resistant to insulin and fail to maintain the blood glucose level." (PMID 31824416, 2019). "The main reason is that excess iron can affect insulin synthesis and secretion, facilitate oxidation of lipids and liver mediated insulin resistance." (PMID 30760217, 2019). "Adipose tissue inflammation can lead to dysregulation of adipocytokine secretion that can induce insulin resistance in insulin-sensitive tissues, such as skeletal muscle and liver." (PMID 30778042, 2019). "In conclusion, it seems that a single injection of vitamin D significantly decreasesserum insulin levels and insulin resistance among patients with polycystic ovarysyndrome." (PMID 31091067, 2019). "Insulin resistance in model rats worsened as the experiment continued, and finally resulted in 62.2% and 113.9% increase in fasting blood insulin and HOMA-IR at week 16, respectively, compared with the control rats." (PMID 31340583, 2019).